PRDX6 (peroxiredoxin 6)
Diseases named in the same sentence as PRDX6 in open-access papers (continued):
Sharing a sentence is not in itself a finding about the gene and the disease.
Cerebral ischemia (6 papers, 2017 to 2025). Restriction of arterial blood supply to the brain associated with insufficient oxygenation to support the metabolic requirements of the tissue. "Thus, Prdx6 may exhibit dual roles in cerebral ischemia, potentially linked to its divergent functions within and outside the cell." (PMID 38671897, 2024). "The transplantation of cerebral endothelial cells (hCMEC/D3) into cerebral ischemia rats may potentially suppress the expression of Prdx6 induced by ischemia injury to control neuroinflammation, which suggests a potential association between Prdx6 and neuroinflammation in cerebral ischemia." (PMID 38671897, 2024). "Increased ROS production and upregulation of PRDX6 were observed after cerebral ischemia injury, implying that oxidative stress induced by cerebral ischemia leads to increased transcription of PRDX6." (PMID 38287382, 2024). "In the present study, we explored the function of Prdx6-iPLA2 in cerebral ischemia/reperfusion injury in both OGD/R microglia/neuron co-culture and MCAO models." (PMID 28424593, 2017). "Hence, there is a need to improve our understanding of the role of Prdx6 in cerebral ischemia to provide reliable validation data for cerebral ischemia treatment." (PMID 38671897, 2024). "To confirm whether Thr177 of PRDX6 was phosphorylated after cerebral ischemia, we immunoprecipitated PRDX6 from cells after OGD/R and probed the immunocomplexes using antiphosphorylation." (PMID 38287382, 2024). "In addition, the aiPLA2 activity of Prdx6 was associated with the secretion of neurotoxic inflammatory factors and a high expression of Toll-like receptor 2/4 (TLR2/4) in cerebral ischemia/reperfusion injury." (PMID 38671897, 2024). "Thus, PRDX6 iPLA2 activity in astrocytes plays a vital role in ROS-induced mitochondrial fission induced by ROS after cerebral ischemia." (PMID 38287382, 2024). "Furthermore, Sp1 inhibition abolishes curcumin-induced Prdx6 upregulation following cerebral ischemia." (PMID 36290607, 2022). "Based on previous research, we hypothesized that the iPLA2 activity of Prdx6 has a critical role in cerebral ischemia/reperfusion inflammatory injury." (PMID 28424593, 2017). "Therefore, we speculate that the role of PRDX6 in promoting mitochondrial fission after cerebral ischemia is related to the activity of iPLA2 and ROS generation." (PMID 38287382, 2024). "Thus, the iPLA2 activity of Prdx6 may play a critical role in cerebral ischemia/reperfusion injury, which might target TLR2/4 inflammatory cascades." (PMID 28424593, 2017). "The role of Peroxiredoxin 6 (Prdx6) in brain ischemia remains unclear." (PMID 28596967, 2017). "In a recent study, a reduction of Prdx6 activity in the MCAO model resulted in increased neuronal apoptosis through the enhancement of the PINK1/PARKIN pathway-mediated mitochondrial autophagy, therefore exacerbating cerebral ischemia-reperfusion injury and apoptosis." (PMID 38671897, 2024). "Whether or not PRDX6 exists in microglia, it does not show any obvious changes after cerebral ischemia." (PMID 38287382, 2024). "However, until now, no study has described the iPLA2 activity of the Prdx6 function in microglia-mediated neuroinflammation and cerebral ischemia/reperfusion." (PMID 28424593, 2017).
liver cancer (6 papers, 2020 to 2025). An epithelial or non-epithelial malignant neoplasm that arises from the liver. "PRDX6, the only non‐selenocysteine glutathione peroxidase in the PRDXs family, has been implicated in promoting late‐stage G2/M arrest in liver cancer cells, inhibiting tumor proliferation in hepatocarcinoma." (PMID 40281661, 2025). "This study offers a theoretical and experimental basis for further research on the mechanism of PRDX6 in liver cancer and new methods for clinical diagnosis and treatment." (PMID 38544826, 2024). "In summary, our results confirm the role of PRDX6 in liver cancer development." (PMID 38544826, 2024). "Therefore, in this study, the effect of PRDX6 expression on the survival of patients with liver cancer was analyzed through data mining." (PMID 38544826, 2024). "Taken together, these findings suggest that PRDX6 may regulate the development of liver cancer partly through the PI3K/Akt/mTOR signaling pathways." (PMID 38544826, 2024). "PRDX6 is expected to be a new target for the diagnosis and treatment of liver cancer." (PMID 38544826, 2024). "Among the 28 unique proteins of the liver tumour model, five proteins have been reported to be associated with liver cancer, including serum amyloid P component (SAMP), alpha-l-fucosidase (AFU), urokinase-type plasminogen activator (UROK), peroxiredoxin 6 (PRDX6), and peroxiredoxin 1 (PRDX1)." (PMID 32095334, 2020). "The present study indicated that PRDX6 plays a key role in the anti-apoptotic properties in liver cancer, and that its overexpression may be a tumor-supportive adaptation in the tumor microenvironment." (PMID 32201510, 2020). "However, the potential effect of PRDX6 on liver cancer remains unclear." (PMID 38544826, 2024). "PRDX6 was highly expressed in tissues surrounding the tumor of HCC patients, so it can be considered that PRDX6, a member of the PRDX family, may have a unique role in the diagnosis and treatment of liver cancer, but the specific mechanism of its action is still uncertain." (PMID 38544826, 2024).
Sepsis (6 papers, 2010 to 2026). Sepsis is defined as life-threatening organ dysfunction caused by a dysregulated host response to infection. "Nothing is known on the induct ability of PRDX6 in young persons affected by sepsis." (PMID 20716329, 2010). "Because reactive oxygen species (ROS) play an important role in sepsis-induced acute kidney injury through activates JNK and p38 MAPK resulting in inflammation and apoptosis, we investigated the effect of PRDX6 on oxidative stress in LPS-induced kidney tissues of mice." (PMID 28881633, 2017). "Thus, it is possible that PRDX6 may play a role in the initiation or severity of ALI after other insults, including sepsis, or in determining recovery from ALI." (PMID 21627785, 2011).
amyotrophic lateral sclerosis (5 papers, 2011 to 2025). Amyotrophic lateral sclerosis (ALS) is a neurodegenerative disease characterized by progressive muscular paralysis reflecting degeneration of motor neurons in the primary motor cortex, corticospinal tracts, brainstem and spinal cord. "Serum levels of Prdx6 in patients with MS were higher than that in control patients with amyotrophic lateral sclerosis and spinocerebellar degeneration." (PMID 38671897, 2024). "Expression of peroxiredoxin 6 is also increased in a mutant SOD1 mouse model of amyotrophic lateral sclerosis." (PMID 21385431, 2011). "Elevated serum PRDX6 levels have previously been reported in patients with MS and neuromyelitis optica spectrum disorder (NMOSD) compared to those with other neurological disorders, such as amyotrophic lateral sclerosis and spinocerebellar degeneration." (PMID 40918143, 2025).
Anxiety (5 papers, 2021 to 2024). Intense feelings of nervousness, tension, or panic often arise in response to interpersonal stresses. "PRDX6 has been linked to depressive and anxiety-like behavior in mice as well as to paroxetine, escitalopram, and sertraline administration in rats." (PMID 39367879, 2024). "Our results demonstrate that female Prdx6−/− mice exhibited anxiety-like behavior, enhanced contextual fear memory, and impaired spatial memory." (PMID 35740098, 2022). "We found that female Prdx6−/− mice showed a higher anxiety-like behavior than males; however, both genders exhibited increased fear responses." (PMID 35740098, 2022). "The present study found that female Prdx6−/− mice exhibited higher anxiety-like behaviors and expressed excessive fear responses (orange box) despite their normal locomotor functions (green box)." (PMID 35740098, 2022). "To verify the influence of anxiety level on spatial memory impairment of Prdx6−/− mice, we subjected the mice to an open field and light/dark transfer test." (PMID 33874992, 2021). "The present study identifies the PRDX6 function in anxiety behavior and memory performance upon acute stress." (PMID 34573048, 2021). "The present study is the first to report the role of PRDX6 in mediating anxiety behavior and memory performance in response to AIS, and in controlling H2O2 levels in the brain." (PMID 34573048, 2021). "Our recent report showed that Prdx6−/− mice exhibited enhanced contextual fear memory, which is also hippocampal-dependent, while their anxiety response evaluated by elevated plus-maze was normal." (PMID 33874992, 2021). "We also demonstrated that Prdx6−/− mice exhibited anxiety behavior and attenuated contextual fear memory responding to AIS." (PMID 34573048, 2021). "Anxiety behavior of Prdx6−/− mice was enhanced after immobilization for 30 min." (PMID 34573048, 2021). "Additionally, AIS induces anxiety in Prdx6−/− mice while attenuating their excessive fear of memory retrieval." (PMID 34573048, 2021). "Our findings may help account for gender differences regarding PRDX6’s function in anxiety." (PMID 35740098, 2022). "Thus, it is worth investigating whether PRDX6 is involved in stress-related anxiety response and memory performance." (PMID 34573048, 2021). "However, it is unknown whether PRDX6 is involved in changes in anxiety response and memory performance upon stress." (PMID 34573048, 2021). "We also evaluated the emotional responses, including anxiety and fear, of female mice lacking the Prdx6 gene." (PMID 35740098, 2022). "Without giving any stressor, female Prdx6−/− mice demonstrate a higher level of anxiety-like behavior, while male Prdx6−/− mice do not show enhanced anxiety behavior unless receiving restraint stress." (PMID 35740098, 2022). "The results obtained from the open field and light/dark transition tests confirmed that spatial memory impairment of Prdx6−/− mice was not affected by their anxiety-like behavior." (PMID 33874992, 2021). "Lack of PRDX6 caused elevated basal H2O2 levels in the hippocampus, basolateral amygdala, and medial prefrontal cortex, brain regions involved in anxiety response and fear memory formation." (PMID 34573048, 2021). "To identify the function of PRDX6 in spatial memory, we subjected Prdx6 knockout (Prdx6−/−) mice to the MWM test, evaluated their motor coordination with the rotarod test, and measured their anxiety behavior with the light/dark transfer tests." (PMID 33874992, 2021). "It is not clear whether the anxiety-like behaviors are due to abnormal development or the dysfunction of other organs since PRDX6 is expressed all over the body." (PMID 35740098, 2022). "However, female Prdx6−/− mice exhibited higher levels of anxiety-like behavior, while male Prdx6−/− mice were not more anxious than their wild-type littermates." (PMID 35740098, 2022). "Moreover, female Prdx6−/− mice exhibited higher anxiety-like behaviors, which is not found in male Prdx6−/− mice." (PMID 35740098, 2022).
colitis (5 papers, 2018 to 2024). Inflammation of the colon. "In acute and chronic DSS-induced colitis models, however, Prdx6 deficiency attenuates the development of colitis." (PMID 32098329, 2020). "Surprisingly, the antioxidative enzyme peroxiredoxin 6 (Prdx6) is a required co-factor for Nox1 activity in wound repair in an animal model of colitis." (PMID 30084091, 2018). "Taken together, we found that a prior 6-week VE effectively reduces inflammation in TNBS-induced colitis, and we suggest that the protective effect of VE may be mediated via the inhibition of NETosis and upregulation of Prdx6 antioxidant." (PMID 37627526, 2023). "Interestingly, they also demonstrated that Prdx6 knockout mice with colitis had less ulceration and lower levels of pro-inflammatory parameters." (PMID 37237891, 2023).
glaucoma (5 papers, 2010 to 2023). Increased pressure in the eyeball due to obstruction of the outflow of aqueous humor. "In contrast, activation of the NRF2/ARE pathway by PLGA.EPO-R76E in glaucoma caused increased expression of Gpx 3, Prdx2, and Prdx6." (PMID 36978804, 2023). "Additionally, many polymorphisms identified in SOD2 and PRDX6 genes may potentially influenced interactions with miRNAs affecting susceptibility to glaucoma." (PMID 33929592, 2021). "These deleterious processes were reversed by raising Prdx6 levels, a finding which has implications for treating or delaying TM cell pathobiology and glaucoma." (PMID 28904819, 2017). "Interestingly, target annotation analysis revealed validated interactions of hsa-miR-6515-3p with eight genes and two out of them, PRDX6 and SOD2, were previously associated with response to oxidative stress, which is a major cause of glaucoma pathogenesis." (PMID 33929592, 2021). "We propose Prdx6 as a potential therapeutic target to guard the TM from oxidative-stress and age-dependent accumulation of ROS by balancing redox-homeostasis to prevent ocular disorders, like glaucoma." (PMID 28904819, 2017). "Targeting of PRDX6 and SOD2 by hsa-miR-6515-3p could be a possible mechanism promoting cellular senescence and impairing antioxidant ability, thus also contributing to glaucoma." (PMID 33929592, 2021). "For example, our work suggests that PRDX6 and SOD3 might contribute significantly to the endogenous antioxidant response, and therefore, exogenously increasing levels of these proteins might be beneficial in delaying or decreasing glaucoma pathogenesis." (PMID 37875948, 2023).
lung adenocarcinoma (5 papers, 2016 to 2025). A carcinoma that arises from the lung and is characterized by the presence of malignant glandular epithelial cells. "PRDX6 is overexpressed in lung adenocarcinoma and especially in patients with resistance to chemotherapy." (PMID 39857679, 2025). "The results obtained in A549 lung adenocarcinoma cells provide a novel insight into the function of Prdx6 in the respiratory system tissues." (PMID 36499590, 2022).
Obesity (5 papers, 2010 to 2023). Accumulation of substantial excess body fat. "A proteomic study conducted in adipose tissue of leptin-deficient (ob/ob) mice treated with leptin recognized PRDX6 as one among 12 functional proteins that by regulating mitochondrial physiology and oxidative stress were implicated in obesity mechanisms." (PMID 31949886, 2019). "PRDX6, an antioxidant enzyme with Ca-independent phospholipase A2 activity, was identified in a recent study as a possible candidate gene underlying a novel obesity locus on chromosome 1q24 in an isolated population of Cilento." (PMID 20532202, 2010). "Further studies to clarify the role of PRDX6 and metabolic diseases, such as obesity and liver dysfunction, are imperative." (PMID 31949886, 2019). "In conclusion, in the present study, we reported a direct role of PRDX6 in the pathological link between obesity and liver diseases by the modulation of noxious oxidative stress and inflammation processes." (PMID 31949886, 2019). "In the present study, innovatively, we reported a pivotal role of PRDX6 in the pathogenesis of obesity and related liver diseases, particularly nonalcoholic fatty liver disease and nonalcoholic steatohepatitis." (PMID 31949886, 2019). "In the present study, Prdx6 was significantly decreased in the obese group compared to the control group, showing that this antioxidant enzyme has an important role in the harmful effects of obesity in some tissues, such as PDL." (PMID 36674516, 2023). "Our results suggest that PRDX6 may have a functional and protective role in the development of obesity-related metabolic disorders such as liver diseases and T2DM and may be considered a potential therapeutic target against these illnesses." (PMID 31949886, 2019). "Obesity negatively impacted the sWAT-MSC secretome, since its anti-oxidant (GCL, Prdx5, Prdx6) and tissue development (Ang, Angptl4, Fstl3, Pgf) activities were lost, while factors promoting osteoporosis and negative vessel remodeling were acquired." (PMID 32727501, 2020). "Obesity negatively impacted sWAT-MSC secretome: the anti-oxidant (GCL, Prdx5, Prdx6) and tissue development (Ang, Angptl4, Fstl3, Pgf) activities were lost, while factors promoting osteoporosis and negative vessel remodeling were acquired." (PMID 32727501, 2020). "PRDX6 is member of the PRDX family of proteins, which may protect against obesity-related pathologies, mainly through elimination of oxidants." (PMID 34327606, 2022). "Increasing evidences suggest that PRDX6 is involved in the pathogenesis of atherosclerosis and T2DM, but its role in the etiopathology of obesity and its complications is still not known." (PMID 31949886, 2019).